IGHV7-81 (immunoglobulin heavy variable 7-81 (non-functional))
Description:
Probable non-functional open reading frame (ORF) of V region of the variable domain of immunoglobulin heavy chains. Non-functional ORF generally cannot participate in the synthesis of a productive immunoglobulin chain due to altered V- (D)-J or switch recombination and/or splicing site (at mRNA level) and/or conserved amino acid change (protein level). Immunoglobulins, also known as antibodies, are membrane-bound or secreted glycoproteins produced by B lymphocytes. In the recognition phase of humoral immunity, the membrane-bound immunoglobulins serve as receptors which, upon binding of a specific antigen, trigger the clonal expansion and differentiation of B lymphocytes into immunoglobulins-secreting plasma cells. Secreted immunoglobulins mediate the effector phase of humoral immunity, which results in the elimination of bound antigens. The antigen binding site is formed by the variable domain of one heavy chain, together with that of its associated light chain. Thus, each immunoglobulin has two antigen binding sites with remarkable affinity for a particular antigen. The variable domains are assembled by a process called V-(D)-J rearrangement and can then be subjected to somatic hypermutations which, after exposure to antigen and selection, allow affinity maturation for a particular antigen.
Synonyms: IGHV781
Gene: Immunoglobulin variable (V) gene on chromosome 14 (106,874,583 to 106,875,071, reverse strand). Ensembl gene ENSG00000211979.
Subcellular location: Secreted; Cell membrane
Gene Ontology:
Molecular function: antigen binding
Biological process: immunoglobulin mediated immune response
Cellular component: extracellular region; plasma membrane
Homologues: Orthologues: chimpanzee IGHV7-81 (81% identical), macaque IGHV7-81 (76% identical), mouse Ighv9-3 (68% identical), mouse Ighv9-2 (65% identical), mouse Ighv9-1 (64% identical), mouse Ighv9-4 (63% identical), rat AABR07065789.1 (58% identical). Paralogues in human: IGHV7-4-1 (85% identical), IGHV1-3 (73% identical), IGHV1-18 (72% identical), IGHV1-2 (70% identical), IGHV1OR15-1 (70% identical), IGHV1-24 (66% identical), IGHV1-45 (66% identical), IGHV1-46 (66% identical), IGHV1-69 (65% identical), IGHV1-69D (65% identical), IGHV1OR21-1 (63% identical), IGHV1-69-2 (62% identical), and 65 more.